HBG1 (hemoglobin subunit gamma 1)
Description:
Gamma chains make up the fetal hemoglobin F, in combination with alpha chains.
Synonyms: PRO2979; HBG-T2; HBGA; HBGR; HSGGL1
Tractability: Small molecule: a structure with a bound ligand is known; it has a binding pocket of medium quality. PROTAC: ubiquitination databases record sites on it.
Gene: Protein-coding gene on chromosome 11 (5,248,269 to 5,249,857, reverse strand). Ensembl gene ENSG00000213934.
Pathways (Reactome):
Hemostasis: Factors involved in megakaryocyte development and platelet production
Gene Ontology:
Molecular function: oxygen carrier activity; heme binding; hemoglobin alpha binding; oxygen binding
Biological process: oxygen transport; carbon dioxide transport; erythrocyte development
Cellular component: hemoglobin complex; cytosol; haptoglobin-hemoglobin complex
Genetic constraint (gnomAD): Loss-of-function variants: 2 observed, 3.41 expected, observed/expected ratio (o/e) 0.59, 90% interval 0.24 to 1.64. That is too few expected variants to judge how well the gene tolerates losing a copy. Missense variants: 43 observed, 49.68 expected, observed/expected ratio (o/e) 0.87, 90% interval 0.68 to 1.12. Synonymous variants: 16 observed, 19.18 expected, observed/expected ratio (o/e) 0.83, 90% interval 0.56 to 1.27.
Homologues: Orthologues: chimpanzee HBG1 (99% identical), zebrafish hbae3 (41% identical), zebrafish hbaa1 (40% identical), zebrafish hbae5 (40% identical), zebrafish si:ch211-5k11.8 (40% identical), zebrafish hbaa2 (39% identical), zebrafish hbae1.1 (37% identical), zebrafish hbae1.2 (37% identical), zebrafish hbae1.3 (37% identical), Drosophila melanogaster glob1 (20% identical), Caenorhabditis elegans glb-34 (19% identical), Caenorhabditis elegans glb-14 (14% identical). Paralogues in human: HBG2 (99% identical), HBE1 (80% identical), HBB (73% identical), HBD (71% identical), HBA1 (40% identical), HBA2 (40% identical), HBQ1 (39% identical), HBZ (39% identical), HBM (33% identical), CYGB (27% identical), MB (24% identical).
Diseases named in the same sentence as HBG1 in open-access papers:
HBG1 is named in the same sentence as 42 diseases in open-access papers, as found by Europe PMC text mining. Sharing a sentence is not in itself a finding about the gene and the disease. The quoted sentences say what the papers report.
sickle cell disease (8 papers, 2020 to 2024). Sickle cell anemias are chronic hemolytic diseases that may induce three types of acute accidents: severe anemia, severe bacterial infections, and ischemic vasoocclusive accidents (VOA) caused by sickle-shaped red blood cells obstructing small blood vessels and capillaries. "Symptoms of sickle cell disease appear during infancy as γ-globin gene (HBG1 and HBG2) transcription switches to HBB, causing a shift from fetal hemoglobin to adult hemoglobin in red cells." (PMID 39655010, 2024). "As part of these efforts, we also utilized XMAS-TREE to enrich for cells that have been edited at several disease-relevant loci including those associated with sickle-cell anemia (i.e., HBG1, HBG2) and Alzheimer’s disease (i.e., AKAP9, PSEN1)." (PMID 33317513, 2020). "Moreover, we mapped de novo L1-ORFeus insertions in cells undergoing ABE8e editing at two disease-relevant loci (BCL11A enhancer and HBG1/2 promoter) currently being evaluated for gene therapy of sickle cell disease and β-thalassemia." (PMID 35760782, 2022).
thalassemia (8 papers, 2018 to 2026). An inherited blood disorder characterized by a decreased synthesis of one of the polypeptide chains that form hemoglobin. "All the noted HBG1 variants were reported for the first time in Pakistani thalassemia patients and carriers." (PMID 37580329, 2023). "The variant rs2071348 was previously reported as a predictor for disease severity in anemic patients with β0-thalassemia/hemoglobin E (p = 3 × 10−15, OR = 4.05), whereas a strong association between HBG1 (rs998870472) and low hemoglobin levels was recently reported (p = 1 × 10−273)." (PMID 37895268, 2023). "Above defined variants of HBA2, HBE1 and HBG1 might confer the thalassemia phenotype in the Pakistani population." (PMID 37580329, 2023). "The results suggested that it may be necessary to design more primers to detect other thalassemia-related genes, such as HBG1 and HBG2, in the future, to implement comprehensive screening." (PMID 35701592, 2022).
beta thalassemia (3 papers, 2014 to 2024). Beta-thalassemia (BT) is characterized by deficiency (Beta+) or absence (Beta0) of synthesis of the beta globin chains of hemoglobin (Hb). "In addition, the analysis also reveals that both Royal Kelantan Malay genomes shared 3 SNP markers; HBG1 (rs1061234), HBB (rs1609812) and BCL11A (rs766432) where all three markers were associated with beta-thalassemia." (PMID 27090252, 2014). "Five genes mapped to hemoglobin subunits (HBG1, HBG2, HBE1, HBB and HBD) involved in beta thalassemia and fetal hemoglobin quantitative trait locus 1 diseases." (PMID 38627641, 2024).
hemoglobinopathies (3 papers, 2018 to 2026). "Leveraging ACG-BEs, we identify novel mutations in the HBG1/2 promoter region that confer efficient activation of γ-globin expression in HUDEP-2 cells—a promising advancement for therapeutic strategies targeting hemoglobinopathies." (PMID 41533583, 2026). "HBG1 induces fetal hemoglobin (HbF) expression and reduces morbidity and mortality in hemoglobin disorders." (PMID 35721103, 2022).
Alpha-thalassemia (2 papers, 2023 to 2024). Alpha-thalassemia is an inherited hemoglobinopathy characterized by impaired synthesis of alpha-globin chains leading to a variable clinical picture depending on the number of affected alleles. "As, HBG1: c.*55delA variant was reported internationally in alpha thalassemia carriers (f = 0.062), β-thalassemia carriers (f = 0.182) and delta-thalassemia (f = 0.116) patients." (PMID 37580329, 2023).
atrial fibrillation (2 papers, 2022). A disorder characterized by an electrocardiographic finding of a supraventricular arrhythmia characterized by the replacement of consistent P waves by rapid oscillations or fibrillatory waves that vary in size, shape and timing and are accompanied by an irregular ventricular response. "Through the immunofluorescence assay, compared with the red blood cells of the control individuals, the expression of HBG1 was higher in the red blood cells of the patients with atrial fibrillation (p < 0.05)." (PMID 35721103, 2022). "The two β-hemoglobins produced by HBG1 and HBDβ-like globin genes may be involved in the occurrence and development of atrial fibrillation through inflammation and stress." (PMID 35721103, 2022). "The expressions of HBG1 and HBD in the red blood cells of the patients with atrial fibrillation were decreased." (PMID 35721103, 2022). "It is further suggested that the two β-like globin genes, HBG1 and HBD, may directly affect the development of left atrial remodeling and atrial fibrillation and the state of blood coagulation by changing the level of hemoglobin or the inflammatory state." (PMID 35721103, 2022). "Therefore, in future research, we will apply for the inclusion of edoxaban in clinical application, then detect the expression of HBG1 and HBD in the blood of patients with atrial fibrillation before and after taking edoxaban, and obtain more sufficient clinical evidence." (PMID 35721103, 2022).
B-cell lymphoma (2 papers, 2024). "Studies in genetic mapping and genome-wide association have identified specific genetic loci associated with SCA, including B-cell lymphoma/leukemia 11A (BCL11A), an Xmn1 variant located upstream of the hemoglobin subunit gamma 1 (HBG1), and the HBS1L-MYB intergenic region." (PMID 38921020, 2024).
COVID-19 (2 papers, 2023 to 2025). A disease caused by infection with severe acute respiratory syndrome coronavirus 2. "First we note that both NFIX31 and BCL11A32 (a distal regulator of globin gene HBG1), which was found to be significant both in the GSMR analysis and also in the COVID-19 host genetics update, are regulators of the foetal haemoglobin (HbF)." (PMID 40240424, 2025). "These proteins either act as positive regulators of cell death (HBG1, HBB, HBD, and HBA1) or are involved in the cellular response to tumor necrosis factor (FABP4, GPD1, THBS1, ASS1, and PCK2), suggesting that apoptosis may be an important cause of heart failure in patients with COVID-19." (PMID 38087340, 2023).
blood disease (1 paper, 2020). A disease that occurs in the blood. "For example, the expression of the HBG1 and HBG2 genes in adults is thought to alleviate the symptoms of β-globin-related blood diseases, and ABE7.10 and ABEmax were successfully used to induce the desired mutation in the HBG1 and HBG2 promoters in HEK293T cells." (PMID 32651459, 2020).
leukemia (1 paper, 2017). A malignant (clonal) hematologic disorder, involving hematopoietic stem cells and characterized by the presence of primitive or atypical myeloid or lymphoid cells in the bone marrow and the blood. "Because HBG1 and HBG2 are involved in the pathogenesis of hematologic diseases, it is not difficult to imagine that lncRNA- HBBP1 may also be involved in hematologic diseases and even leukemia." (PMID 29221148, 2017).
lung adenocarcinoma (1 paper, 2016). A carcinoma that arises from the lung and is characterized by the presence of malignant glandular epithelial cells. "Of the 16 distinguishing proteins, 8 were significantly elevated in lung adenocarcinoma (COPG1, STOML2, HYOU1, PDIA4, EPRS, APEX1, LRPPRC and NANS) whereas 8 proteins were significantly decreased in lung adenocarcinoma (SPTB, SPTA1, ANK1, SLC4A1, HBG1 and HBG2)." (PMID 27799870, 2016).
melanoma (1 paper, 2017). A malignant, usually aggressive tumor composed of atypical, neoplastic melanocytes. "These include hemoglobin genes (HBB, HBG1, HBG2) in the peripheral blood-derived cell line KU812, MIA (melanoma inhibitory activity) in the melanoma-derived cell line A375 as well as insulin (Ins1, Ins2) and islet amyloid polypeptide (Iapp) in the mouse pancreatic beta cell line Beta-TC6." (PMID 28687070, 2017).
myeloid leukemia (1 paper, 2022). A clonal proliferation of myeloid cells and their precursors in the bone marrow, peripheral blood, and spleen. "Interestingly, previous evidence shows that HBG1, KLF1, and KLF3 are up-regulated in the β globin knockout human erythroid progenitor cell model, relative to controls and in human myeloid leukemia cells." (PMID 35627314, 2022).
pancreatic cancer (1 paper, 2022). "In late-stage pancreatic cancer,cellular oxidant detoxification and oxygen transport, including hemoglobinsubunit γ-1 (HBG1), are upregulated." (PMID 35605973, 2022).
schizophrenia (1 paper, 2019). A major psychotic disorder characterized by abnormalities in the perception or expression of reality. "Model selection using glinternet to allow for first-order interactions identified five peptides from APOE, A2AP, HBA, HBG1 and SHBG whose effect on the probability of having schizophrenia was modified by sex." (PMID 30745560, 2019). "The five frequently selected interactions suggest that the sex of a subject was modifying the effects of peptides from APOE, A2AP, HBA, HBG1, and SHBG on the probability of having schizophrenia." (PMID 30745560, 2019).
squamous cell carcinoma (1 paper, 2022). A carcinoma arising from squamous epithelial cells. "HBG1 and HBG2, the gamma globin genes, have been reported to have low expression in NSCLC, including adenocarcinoma and squamous cell carcinoma." (PMID 35354498, 2022).
cancer (3 papers, 2021 to 2023). A tumor composed of atypical neoplastic, often pleomorphic cells that invade other tissues. "HBG1 is only expressed in the fetal liver, spleen, and bone marrow, so targeting its intron sequence in cancer cell lines is expected to have minimal on-target effect." (PMID 34215850, 2021).
adenocarcinoma (2 papers, 2016 to 2022). A common cancer characterized by the presence of malignant glandular cells. "Consistent with our proteomic data, mRNA expression of APEX1, HYOU1, PDIA4, NANS, LRPPRC, EPRS and COPG1 were significantly (Mann–Whitney U < 0.05) higher in adenocarcinoma compared to control whereas mRNA abundance of HBG1, HBG2, HBD, and PTRF were significantly (Mann–Whitney U < 0.05) lower." (PMID 27799870, 2016).
Tumor (1 paper, 2022). "Tumor cells expressing the Erythroid-like signature in patients 2 and 5 expressed early-stage erythroblast markers, but had lower expression of mid and late stage erythroid markers HBG1, HBG2, HBA2, and HBB than tumor-associated erythroid cells." (PMID 36008377, 2022).
HBG1 also shares sentences with these, for which no sentence is quoted: infection (6 papers); dyslipidemia (2); Alzheimer disease (1); anemia (1); breast carcinoma (1); cholera (1); coronary atherosclerosis (1); deep vein thrombosis (1); delta-thalassemia (1); diabetes (1); heart failure (1); hematologic diseases (1); Hyperglycemia (1); iron deficiency (1); microcytic anemia (1); neonatal anemia (1); ovarian carcinoma (1); paroxysmal AF (1); prostatic neoplasms (1); red blood cell disorders (1); Stroke (1); venous thromboembolism (1); virus infection (1).